EGFR (epidermal growth factor receptor)
Diseases named in the same sentence as EGFR in open-access papers (continued):
Sharing a sentence is not in itself a finding about the gene and the disease.
tumor (continued). "AFM24 is effective against a variety of EGFR-expressing tumor cells regardless of EGFR expression level and KRAS/BRAF mutation status." (PMID 36341333, 2022). "But studies in various cancers, including GBM, showed that overexpression of PKC contributes to tumor pathogenesis and seems to be involved in EGFR, PI3K/Akt, Ras/MEK/MAPK, hedgehog, and TNFα signaling, which are deregulated in GBM and are deemed to be potent targets." (PMID 35785151, 2022). "In this setting, tumor cells are attracted to the epidermal growth factor receptor (EGFR) oncogene." (PMID 35203586, 2022). "EGFR and EphA2 were expressed at significantly higher levels in cancer tissues than in normal tissues, and levels increased to significant degrees with advancing tumor cell grade." (PMID 35668076, 2022). "In NSCLC cells, except that increased MMP2/14 could degrade the extracellular matrix and enable tumor cells to invade into the area nearby, it also provided the opportunity to transactivate EGFR." (PMID 35013118, 2022). "The reasons may include potential antagonism between platinum drugs and EGFR-TKIs or that cell cycle-specific chemotherapy drugs are difficult to play a role because EGFR-TKIs arrest the tumor cell cycle at G1 phase." (PMID 36172729, 2022). "In our study, similar to previous studies, the detection of plasma EGFR mutation was associated with never-smoker and higher tumor burden such as a higher N stage, and brain or intrathoracic metastasis." (PMID 35207417, 2022). "The mRNA and EGFR proteins of tumor cells should be further studied." (PMID 35387120, 2022). "The growth and invasion of Epithelial-mesenchymal transition-induced tumor cells could be inhibited by PD.173074 through EGFR pathway." (PMID 36199146, 2022). "However, most individuals treated with TKI therapy for EGFR-mutant NSCLC will develop tumor resistance to TKI therapy." (PMID 36010982, 2022). "Blocking EGFR by anti–EGFR monoclonal antibody could effectively prevent the aggregation of cancer cells and reduce the pulmonary metastasis of tumor." (PMID 36059616, 2022). "Compared with either single-agent treatment, combined targeting of MET and EGFR resulted in enhanced reductions in tumour volumes and weights, accompanied by decreased activation of downstream signaling pathways in vivo, and the results were consistent with those of the in vitro experiments." (PMID 35101055, 2022). "To date, the principal indications for liquid biopsy in CRC are: i) RAS and BRAF testing as substitute for tumor tissue analysis in stage IV metastatic CRC and ii) RAS mutational profiling for rechallenge in patients resistant to first line anti-EGFR therapies." (PMID 35837109, 2022). "One major obstacle for translating plasma EGFR mutation testing into routine clinical practice is the lack of standardization of methods for assessing tumor mutations." (PMID 36232650, 2022). "Importantly, plasma ACh levels and tumor ChAT expression of human patients with NSCLC correlated with response to EGFR-TKI treatment and progression-free survival." (PMID 36048538, 2022). "Tumor uptake was dependent on EGFR density, with the HT-29 xenograft having the highest expression with the highest tumor uptake and SW620 xenograft having the lowest: HT-29 (19.1 ± 1.4% IA/g) > DLD-1 (14.7 ± 0.3% IA/g) > MDA-MB-231 (12.8 ± 1.2% IA/g) > SW620 (4.4 ± 0.9% IA/g)." (PMID 36145664, 2022). "Positive EGFR expression of the tumor was found in 64.71% (11/17) nude rats." (PMID 36591483, 2022). "For the HER 2 + tumor subtype, all genes implicated were located at chromosome 17q, where we distinguished relevant pathways such as the ERBB2, ERBB, and epidermal growth factor receptor (EGFR) or the negative regulation of ERBB." (PMID 36119512, 2022).
tumor (continued). "Additionally, they used the same flies to show that HSD promoted EGFR-induced neoplasia in an ImpL3-dependent manner." (PMID 36091180, 2022). "Further understanding the diversity of tumour cells with different EGFR statuses may promote the improvement of clinical treatment of lung metastasis patients with tyrosine kinase inhibitors." (PMID 36336787, 2022). "In addition, more than 60% of NSCLC carcinomas express EGFR, being the main NSCLC tumor driver when activating mutations are present." (PMID 35455052, 2022). "In our study, age, gender, smoking history, histology, tumor differentiation, EGFR mutation status, CEA level, and OS were not statistically significant factors related to the diagnostic accuracy of ROSE." (PMID 35330451, 2022). "As early as 2012, scientists from Duke University designed a gemcitabine polymer and then hybridized it with the anti-EGFR RNA aptamer (E07) by hydrogen bond base pairing, so the aptamer–gemcitabine hybrid can block the EGFR downstream signal pathway and poison the tumor cells with gemcitabine." (PMID 36544906, 2022). "Exosomes derived from EGFR-mutated adenocarcinoma serum could be a potential mediator of hybrid EMT and tumor invasion." (PMID 35954442, 2022). "Moreover, systemic administration of the αEGFR-172 ADC in mice strongly inhibited the growth of B16F10 tumors in a manner that depends on the expression of EGFR in the tumor cells." (PMID 36442099, 2022). "Besides ATR mutations, common mutated genes (BRCA1, EGFR, and ROS1) that characterize LUAD were also found in 5 tumor samples." (PMID 35712480, 2022). "Anti-EGFR antibodies have also been shown to cross-prime NK and dendritic cells, which may additionally lead to tumor-specific cellular immunity." (PMID 36291769, 2022). "The enhancement of EGFR in the lesser curvature tumor may indicate its new prognostic value and provide new clues for GC treatment." (PMID 35984169, 2022). "Moreover, mutational activation of EGFR and ligand stimulation of wild-type EGFR has been reported to result in Beclin 1 tyrosine phosphorylation, which leads to autophagy suppression, tumor growth, and tumor dedifferentiation in NSCLC xenografts." (PMID 37192859, 2022). "Thus, there is a significant unmet need for therapies that are effective and safe in patients with EGFR-expressing solid tumors and can overcome currently documented inherent or acquired tumor resistance mechanisms to therapies targeting EGFR." (PMID 36185288, 2022). "ASN007 treatment impeded tumor cell growth and the cell cycle in EGFR TKI-resistant cells." (PMID 34973117, 2022). "Interference function of EGFR/MET attenuated anoikis resistance of tumor cells." (PMID 35428350, 2022). "In addition, Western blotting demonstrated that T12/P-Lipo had a strong inhibitory effect on EGFR/Erk/Akt tumor growth signaling pathway, which was highly consistent with the in vitro results." (PMID 36015232, 2022). "Many studies have shown that EGFR-TKIs and PD-1/PD-L1 inhibitors can affect tumor metabolism." (PMID 36034789, 2022). "In contrast, ER/21-PE24, which has an intermediate affinity for EGFR and a relatively fast dissociation rate, tends to detach from normal cells with low EGFR density, but remains on tumor cells with high EGFR density, enabling it to distinguish tumor cells from normal cells." (PMID 36555466, 2022). "A new type of a bispecific antibody that engages simultaneously EGFR on tumor cells and CD3 on T cells was designed to prevent its binding to EGFR expressed in healthy tissues (a masked form) but to become activated by proteases (an unmasked form) in the tumor microenvironment." (PMID 36185288, 2022).
tumor (continued). "Additionally, EGFR amplification, PTEN loss, and regular unmethylated MGMT have all been linked to an increase in tumor blood volume." (PMID 36654821, 2022). "Thus, targeted phagocytosis with EGFR+ tumour cells was seen for all macrophage-like states in vitro." (PMID 36555321, 2022). "Indeed, such metabolism promotes the expression of PD-L1 in tumor cells by the epidermal growth factor receptor (EGFR)/extracellular signal-regulated kinase (ERK)/C-Jun pathway." (PMID 35392976, 2022). "Intra-patient EGFR mutations identified in the isolated CTCs were perfectly concordant with the mutations found in tumor-derived cfDNA, but not in tissue biopsy." (PMID 35664056, 2022). "EGFR overexpression is detected in 68% of HCC cases and is linked to more aggressive tumors with a high proliferation index, intrahepatic metastasis, de-differentiation, and tumor size." (PMID 35039485, 2022). "Lower tumor mutational burden (TMB), a lower number of tumor-infiltrating lymphocytes (TILs), and poor response to ICI have also been reported for EGFR-mutated NSCLC, and any potential role of ICI in cases with EGFR mutations is currently discussed." (PMID 35562908, 2022). "Tumor-derived exosomal circRNA_102481 may promote resistance to epidermal growth factor receptor tyrosine kinase inhibitors (EGFR-TKIs) in NSCLC via the miRNA-30a-5p/ROR1 axis." (PMID 35382838, 2022). "Unlike categorical biomarkers for oncogene-addicted NSCLC such as epidermal growth factor receptor (EGFR), PD-L1 as an immunotherapy biomarker is continuous, spatially and temporally variable, and impacted by complex immune machinery in the tumor immune microenvironment (TIME)." (PMID 36498802, 2022). "Additionally, tumor tissues derived CAFs significantly enhanced A549/PC-9 cells’ resistance to EGFR TKIs namely Erl and Gef." (PMID 35831824, 2022). "EGFR, which is natively expressed on epithelial cells in the skin and lung, is overexpressed in a wide range of cancers including bladder cancer, lung cancer, colorectal cancer, and breast cancer, where it is involved in tumor progression and metastasis." (PMID 35479092, 2022). "Interestingly, a discrepancy in EGFR expression between the primary tumor and metastatic brain lesions was observed in a patient under long-term CTX treatment who eventually acquired resistance." (PMID 35409179, 2022). "The unexpected result regarding worse survival in patients with high plasma exposure to osimertinib or erlotinib might be explained by the occurrence of tumor resistance to EGFR-TKIs through off-target mechanisms including amplification of MET and HER2." (PMID 36145591, 2022). "According to previous studies, C7 contains several oncogenes; epidermal growth factor receptor (EGFR) (7p12) and Met (7q31) may play important roles in the development of biliary tract carcinogenesis and/or tumor progression." (PMID 35589822, 2022). "However, high EGFR expression failed to select a group with poor prognosis in AGC, while many previous studies reported that the overexpression of EGFR was related to tumor growth and drug resistance." (PMID 35723316, 2022). "Indeed, active MMP-9 expression can occur in up to 73% of EGFR amplified tumours and is strongly correlated with EGFRvIII expression, with MMP-9 expression occurring in up to 83% of EGFRvIII-expressing tumours." (PMID 36497413, 2022). "In summary, our findings demonstrated that ANXA1 promoted tumor progression by activating EGFR signaling, which revealed that ANXA1 might be a prognostic predictor and underlying therapeutic target for BLCA." (PMID 34991599, 2022). "It is not understood why TKIs do not work in tumours driven by EGFR overexpression but do so in tumours bearing classical activating EGFR mutations, although the latter develop resistance in about one year." (PMID 35158954, 2022). "As can be shown, EGFR is an important anti-tumor target of MT." (PMID 36110092, 2022).
tumor (continued). "If EGFR is overexpressed, it may therefore lead to uncontrolled cell growth and thus tumor formation." (PMID 36497451, 2022). "Although targeting EGFR using cetuximab has shown some benefits for HPV-negative tumours, the outcome of EGFR inhibition for HPV-positive HNSCC was the opposite causing a clear inferior response and poorer survival outcome as compared with standard treatment modalities." (PMID 36333293, 2022). "In the last 15 years, molecular studies have highlighted the role e of genes called “Oncodrivers” involved in tumor genesis, particularly Epidermal Growth Factor Receptor (EGFR) and Anaplastic Lymphoma Kinase (ALK), which have become the target of specific and selective drugs." (PMID 35092185, 2022). "Our findings suggest that CDCA may enhance the anti-tumor effects of sorafenib via inhibition of the EGFR/Stat3 signaling pathway." (PMID 35252007, 2022). "For one patient, a targetable EGFR Ex19Del was detected in plasma-derived ctDNA, while multiple samples of pleural fluid did not contain enough tumor cells for tissue mutation analyses." (PMID 36413862, 2022). "Conversely, using EGFR targeting monoclonal antibodies may activate M2 macrophages, which promote tumor progression." (PMID 36145516, 2022). "Although most patients would be expected to be negative for EGFR mutations, the pre-test probability of harbouring an EGFR-mutation-positive tumor is higher in certain patient populations such as non-smokers." (PMID 36290901, 2022). "Additionally, activation of epidermal growth factor receptor (EGFR) in MLPS tumor cells by macrophage-secreted ligand heparin-binding EGF-like growth factor (HB-EGF) plays a crucial role in this process." (PMID 36230502, 2022). "Immune checkpoint inhibitors (ICIs) have adverse effects and poor efficacy in patients with an EGFR mutation or a secondary T790M mutation, largely because of low tumor mutational burden and a noninflamed tumor microenvironment." (PMID 35840984, 2022). "This may block the induction of autophagy and inhibit apoptosis in response to EGFR‐TKIs, thereby promoting cell survival and tumor growth." (PMID 35593080, 2022). "Although EGFR is attractive as an overexpressed tumor target, it is also expressed in normal tissues, and thus any therapeutic strategy must consider the potential for on-target off-tumor toxicity." (PMID 35935988, 2022). "This was indicated by not only a faster reduction in tumour size upon aPD-1 + erlotinib therapy compared to EGFR inhibition alone, but also by tumours remaining in a partial response (PR) state until the end of the experiments, in contrast to the erlotinib group." (PMID 36010935, 2022). "The cross-reactivity of the ER-PE24 variants with both human and murine EGFR facilitated the comparison of the antitumor efficacy and systemic toxicity of ER-PE24 ITs with the highest and intermediate affinity for EGFR in the EGFR-overexpressing tumor xenograft mouse model." (PMID 36555466, 2022). "Researchers found that deguelin could inhibit the proliferation, invasion, metastasis, and autophagy of tumor cells by regulating many signal pathways (e.g., EGFR/IGF1R-Akt, MAPK, and mTOR)." (PMID 35637651, 2022). "Liquid biopsy can confirm the EGFR mutation status without the need for a surgical resection of the tumor, which is useful for analyzing EGFR mutations in unresectable MPLC cases." (PMID 35740676, 2022). "Additionally, activated EGFR signaling leads to the proliferation of epidermal cells to induce tumor formation under hypoxic conditions." (PMID 34976156, 2022). "In addition, depending on the genotype of the tumor and its location, antibodies targeting the vascular endothelial growth factor (such as bevacizumab) or epidermal growth factor receptor (such as cetuximab) are added to the chemotherapy regimen." (PMID 36230796, 2022).
tumor (continued). "In the univariate analysis for overall survival, age (≥60 years), ECOG PS, tumor grade (moderately, and poorly differentiated tumors), EGFR wild-type status and the absence of response were associated with a worse OS." (PMID 36661676, 2022). "Moreover, GP1 displayed increased expression of angiogenic features (e.g., ANGPTL4, EGFR, AAMP) and complement and coagulation cascade components (e.g., C1, C7, C8, C9, PLG, SERPINE1), which have been associated with aggravated tumor invasion." (PMID 35440542, 2022). "In addition, the combination of SRC inhibitors and EGFR blocking antibodies significantly inhibited tumor growth and prolonged the survival rate of mice." (PMID 35891968, 2022). "In particular, we investigated our hypothesis that EGFR was involved in the tumor suppression and macrophage differentiation induction effects of CB1 activation." (PMID 35641479, 2022). "Interestingly, Case 3 adjacent tissue had higher Cy5.5-N24-EGF signal compared to tumor, findings that were corroborated by anti-EGFR IHC scorings." (PMID 36082359, 2022). "Furthermore, identical EGFR genotypes were observed in 12 patients with an ISP and an associated SNSCC when the DNA from each tumour was separately extracted, providing the first molecular evidence to support the role of ISP as a precursor for SNSCC." (PMID 35053553, 2022). "It is unclear how the presence of CD3+ T cells overrides the tumor promoting effects of EGFR." (PMID 35957892, 2022). "The study revealed that patients with EGFR or ALK tumor mutations did not benefit from chemotherapy plus atezolizumab compared with chemotherapy alone." (PMID 36426286, 2022). "Second, whether adjuvant EGFR-TKIs can lead to tumor resistance untimely and develop complex resistance mechanisms that without effective drugs in the absence of bulky tumor burden remains unclear." (PMID 35346117, 2022). "Tumor EGFR binding of afatinib was predicted to be extensive for and comprised 72.17% of all tissue binding, whereas for erlotinib and osimertinib the model showed that only a minor fraction of the tissue fraction bound to EGFR (1.89 and 1.85%, respectively)." (PMID 35890095, 2022). "Moreover, EGFR-positive exosomes were shown to have the ability to drive DCs to generate tolerogenic DCs that can induce tumor-specific regulatory T cells." (PMID 35158999, 2022). "Finally, inhibition of AhR signals efficiently prevented tumor growth and development of EGFR TKIs resistance, eventually improved the outcome of EGFR TKIs, and described a promising therapeutic strategy for NSCLC." (PMID 35831824, 2022). "In cancer, EGFR activity drives tumorigenesis in different types of cancer since sustained activation triggers signaling pathways favoring cell survival, proliferation and migration that all contribute to tumor progression." (PMID 35646668, 2022). "By binding with tyrosine kinase, EGFR TKIs can inhibit the activation of tyrosine kinase and block downstream signaling pathways, ultimately inhibiting the proliferation and metastasis of tumor cells and promoting the apoptosis of tumor cells." (PMID 36508072, 2022). "One mechanism by which co-occurring genetic alterations could affect therapeutic sensitivity to EGFR TKI treatment is via the modulation of tumor cell apoptosis." (PMID 35579943, 2022). "Tumour-derived exosomes may also enhance tumorigenesis by secretion of epidermal growth factor receptor (EGFR) ligands like amphiregulin." (PMID 35735486, 2022). "However, the conditions that allow for the exposure of this epitope preferentially occur under tumor-specific conditions as a result of EGFR overexpression." (PMID 36456600, 2022). "The relationship between CD82 palmitoylation mutation and EGFR and c-Met has not been clarified so far, including the theoretical mechanism for its expression and localization changes in tumor cells and specific metabolic pathways." (PMID 35538033, 2022).